STK33 (serine/threonine kinase 33)
Description:
Serine/threonine protein kinase required for spermatid differentiation and male fertility. Promotes sperm flagella assembly during spermatogenesis by mediating phosphorylation of fibrous sheath proteins AKAP3 and AKAP4 (By similarity). Also phosphorylates vimentin/VIM, thereby regulating the dynamic behavior of the intermediate filament cytoskeleton (By similarity).
Synonyms: SPGF93
Tractability: Small molecule: a structure with a bound ligand is known; a high-quality ligand is known; it belongs to a druggable protein family. PROTAC: it is named in the literature on targeted protein degradation; ubiquitination databases record sites on it; a small molecule that binds it is known.
Target class: CAMK protein kinase group; CAMK protein kinase unique family; Kinase; Enzyme; Protein Kinase
Chemical probes: ML280, ML281
Gene: Protein-coding gene on chromosome 11 (8,391,864 to 8,594,292, reverse strand). Ensembl gene ENSG00000130413.
Subcellular location: Cytoplasm; Cytoplasm, cytoskeleton; Cytoplasm, perinuclear region
Subcellular location (Human Protein Atlas): Flagellar centriole; Nucleoplasm; Cytosol; Mid piece; Nucleoli
Gene Ontology:
Molecular function: protein serine/threonine kinase activity; protein serine kinase activity; ATP binding; protein kinase activity
Biological process: negative regulation of proteasomal ubiquitin-dependent protein catabolic process; negative regulation of protein polyubiquitination; peptidyl-threonine phosphorylation; spermatogenesis; manchette assembly; mitotic DNA damage checkpoint signaling; protein autophosphorylation
Cellular component: cytoplasm; manchette; nucleus; cytoskeleton; perinuclear region of cytoplasm
Genetic constraint (gnomAD): Loss-of-function variants: 27 observed, 36.81 expected, observed/expected ratio (o/e) 0.73, 90% interval 0.54 to 1.01. The upper end of that interval is the gene's LOEUF score, 1.01, which puts it in group 4 of 6, group 1 being the genes least tolerant of losing a copy. Missense variants: 541 observed, 515 expected, observed/expected ratio (o/e) 1.05, 90% interval 0.98 to 1.13. Synonymous variants: 185 observed, 173.95 expected, observed/expected ratio (o/e) 1.06, 90% interval 0.94 to 1.2.
Homologues: Orthologues: chimpanzee STK33 (99% identical), macaque STK33 (95% identical), rabbit STK33 (81% identical), dog STK33 (77% identical), pig STK33 (72% identical), rat Stk33 (69% identical), mouse Stk33 (67% identical), guinea pig STK33 (66% identical), tropical clawed frog stk33 (47% identical), zebrafish stk33 (45% identical), Caenorhabditis elegans K02E10.7 (16% identical). Paralogues in human: DCLK2 (26% identical), DCLK1 (25% identical), CAMK1D (22% identical), CAMK1G (22% identical), CAMK1 (21% identical), PSKH1 (21% identical), PSKH2 (21% identical), CAMKV (20% identical), DCLK3 (20% identical), PHKG1 (20% identical), CAMK2D (20% identical), CAMK2B (19% identical), and 10 more.
Diseases named in the same sentence as STK33 in open-access papers:
STK33 is named in the same sentence as 43 diseases in open-access papers, as found by Europe PMC text mining. Sharing a sentence is not in itself a finding about the gene and the disease. The quoted sentences say what the papers report.
lung cancer (7 papers, 2017 to 2025). A malignant neoplasm involving the lung. "Phosphorylation of serine/threonine kinase 33 (STK33) by extracellular signal-regulated kinase (ERK) has been implicated in lung cancer metastasis, but its role in thrombin-induced airway inflammation remains to be determined." (PMID 41121245, 2025). "Additionally, the remarkable expression level of STK33 has been linked to lung cancer patients’ poor survival outcomes." (PMID 38413579, 2024). "Next, to analyze the CDK inhibitory function of Z29077885, we first selected model cell lines, MDA-MB-231 breast cancer cells and A549 lung cancer cells, in which the function of STK33 is well understood." (PMID 38087254, 2023). "Several tumor cell lines including pancreatic, colorectal, breast and lung cancer also express STK33." (PMID 29100402, 2017). "Notably, previous research has reported a higher protein expression of STK33 in various histological types of lung cancer tissues compared with benign lung tissues." (PMID 38413579, 2024). "Previous studies have demonstrated that STK33 is overexpressed in hypopharyngeal squamous cell carcinoma, hepatocellular carcinoma, human lung cancer, and pancreatic cancer and the increased expression of STK33 may subsequently promote tumorigenesis and disease progression." (PMID 30760631, 2019). "The STK33/ERK signaling pathway, for example, may regulate lung cancer cells' malignant biological activity." (PMID 36816358, 2023).
breast carcinoma (6 papers, 2017 to 2025). "For example, pathway analysis reveals the association of highly expressed genes in DAB2IP-low ER+ tumors with STK33, a protumorigenic kinase that increases proliferation in breast cancer cells and has been associated with advanced colorectal and pancreatic malignancies." (PMID 39418101, 2024). "In our experimental setup STK33 interacted with hypoxia-stabilized HIF-1α in HCT-116 colon, MIA PaCa2 and MDA-MB-231 breast cancer cells suggesting a potential role of STK33 in hypoxic tumors." (PMID 29100402, 2017). "Abrogation of STK33 was associated with impaired proliferation in MIA PaCa2 pancreas, HCT-116 colon and MDA-MB-231 breast cancer cells." (PMID 29100402, 2017). "STK33 expression analysis revealed markedly higher levels in TNBC cell lines (MDA‐MB‐231 and HCC1806) compared to ER (+) (MCF‐7 and T47D) and HER2 (+) (SK‐BR‐3 and JIMT1) breast cancer cell lines, where expression was nearly undetectable." (PMID 40908551, 2025). "A positive correlation was recorded between STK33 and CCAR1 in basal‐like breast cancer." (PMID 40908551, 2025). "Moreover, the results indicated that elevated expression of STK33 and CCAR1 correlated with poor survival in breast cancer, suggesting that the STK33‐CCAR1 axis is likely to be a robust biomarker for predicting the prognosis of TNBC." (PMID 40908551, 2025).
pancreatic cancer (4 papers, 2017 to 2024). "In an attempt to address this issue we found that STK33 overexpression in MIA PaCa2 pancreatic cancer cells was associated with augmented kinase activity and expression of PKD2, another serine/threonine kinase described as a client of HSP90." (PMID 29100402, 2017). "The results showed that the iron chelator, ferroptosis inhibitor, and glutathione significantly alleviated the inhibitory effects of reduced MACC1-AS1 or STK33 expression on the viability of pancreatic cancer cells." (PMID 38413579, 2024). "In terms of clinical application, it was attempted to analyze the expression level of MACC1-AS1, STK33 and both genes in pancreatic cancer patients and their prognostic significance." (PMID 38413579, 2024). "The results revealed that compared with cells with MACC1-AS1 overexpression alone, siSTK33 co-transfection and STK33 inhibitors reduced the gemcitabine IC50 value in pancreatic cancer cell lines exhibiting a high expression level of MACC1-AS1 to some extent." (PMID 38413579, 2024). "Promoter analysis using a HIF-specific reporter revealed that overexpression of STK33 was able to partially restore HIF-1α transcriptional activity in MIA PaCa2 pancreatic cancer cells treated with PU-H71 and incubated in hypoxic atmosphere." (PMID 29100402, 2017). "Therefore, the degree of oxidative stress in pancreatic cancer cells was evaluated by downregulating MACC1-AS1 or STK33 expression." (PMID 38413579, 2024). "Furthermore, it was revealed that stable overexpression of STK33 enhanced the resistance of pancreatic cancer cells to gemcitabine." (PMID 38413579, 2024). "Additionally, knockdown of MACC1-AS1 shortened the half-life of STK33, highlighting a significant influence on the stability of STK33 in pancreatic cancer cells." (PMID 38413579, 2024). "Pancreatic cancer cells were subsequently treated with downregulated MACC1-AS1 or STK33 using AKT-IN-9 (an Akt inhibitor), Nrf2-IN-1 (an NRF2 inhibitor), JSH-23 (an NF-κB inhibitor), SB203580 (a p38 inhibitor), SP600125 (a JNK inhibitor), and SCH772984 (an ERK inhibitor)." (PMID 38413579, 2024). "Additionally, in both gemcitabine-treated normal pancreatic cancer cells and drug-resistant cells at low concentrations, STK33 protein expression was upregulated, with its higher expression level was found in drug-resistant cells." (PMID 38413579, 2024). "Furthermore, STK33 is overexpressed in hypopharyngeal squamous cell carcinoma, hepatocellular carcinoma, human large cell lung cancer, and pancreatic cancer and the increased expression of STK33 may subsequently promote tumorigenesis and disease progression." (PMID 30760631, 2019). "When investigating such a possibility we found that overexpression of STK33 was paralleled by an augmented PKD2 expression and activity particularly in MIA PaCa2 pancreatic cancer cells as demonstrated by the western blot analysis." (PMID 29100402, 2017). "Our findings demonstrate that deletion of STK33 markedly reduced hypoxia-induced accumulation of HIF-1α in colon and pancreatic cancer cells." (PMID 29100402, 2017). "In addition, compared with cells with MACC1-AS1 overexpression alone, co-transfection of STK33 siRNA and MACC1-AS1 overexpression plasmid in pancreatic cancer cell lines reduced cell viability and exhibited time-dependent effects." (PMID 38413579, 2024). "Considering the well-established oncogenic functions of MACC1-AS1/STK33 in the previous findings, the present study attempted to unravel the upstream mechanism through which MACC1-AS1/STK33 contributes to gemcitabine resistance in pancreatic cancer cells." (PMID 38413579, 2024). "In addition, knockdown of STK33 in KRAS mutant epithelial cancer cell lines from different origins (including colorectal, breast, and pancreatic cancers) led to impaired colony formation in vitro and slower growth in vivo." (PMID 34955846, 2021).
colorectal cancer (3 papers, 2017 to 2019). A primary or metastatic malignant neoplasm that affects the colon or rectum. "The results showed that STK33 was overexpressed in human colorectal carcinoma HCT15, HCT116, HCT8, and DLD1 cells." (PMID 30760631, 2019). "Our study has revealed STK33 as an essential molecule for progression of pancreatic and colorectal cancers in which the tumor environment was reported to be highly hypoxic." (PMID 29100402, 2017). "In order to interrogate the levels of STK33 in tumor specimens, our study involved a cohort of 68 patients with colorectal cancer (CRC) as well as a set of 61 patients with pancreatic ductal adenocarcinoma (PDAC)." (PMID 29100402, 2017). "Here we report that elevated STK33 expression correlates with advanced stages of human pancreatic and colorectal carcinomas." (PMID 29100402, 2017). "What is more, STK33 was moderately expressed in human colorectal carcinoma SW480 and HT29 cells." (PMID 30760631, 2019). "In our study, we found that STK33 promotes the transformation of colorectal carcinoma." (PMID 30760631, 2019). "STK33 phosphorylated ERK2 and increased the activity of ERK2 and promote the tumorigenesis of colorectal cancer HCT15 cells." (PMID 30760631, 2019).
gastric cancer (3 papers, 2020 to 2022). A primary or metastatic malignant neoplasm involving the stomach.
Infertility (3 papers, 2023 to 2025). "For example, STK33 phosphorylates multiple proteins linked to infertility and is required for the differentiation of round spermatids into functional sperm." (PMID 41465693, 2025). "Men in a single family were discovered to have a frameshift mutation in the STK33 gene leading to infertility that phenocopied the Stk33 knockout mice." (PMID 38781365, 2024). "We found that STK33 is mutated in infertile patients with NOA, but Stk33-/KI and Stk33−/− mice were sterile with decreased number of sperm with oligoasthenoteratozoospermia, and Stk33KI/KI mice were subfertile with decreased number of sperm and asthenozoospermia." (PMID 37146716, 2023).
acute myeloid leukemia (2 papers, 2021). Acute myeloid leukemia (AML) is a group of neoplasms arising from precursor cells committed to the myeloid cell-line differentiation. "Knockdown of STK33 in acute myeloid leukemia cells led to upregulation of a set of genes (STK33-UP), suggesting a potential inhibition of these genes by STK33." (PMID 34503297, 2021). "The top enriched upregulated gene set was STK33 SKM UP (FDR p = 0.002), containing the genes upregulated in SKM-1 acute myeloid leukemia (AML) cells after knockdown of STK33." (PMID 34955846, 2021).
asthenozoospermia (2 papers, 2023 to 2024). "STK33 absence is associated with asthenozoospermia, but other studies suggest a role of STK33 in tumorigenesis and regulation of extracellular signal–regulated kinase (ERK) signaling pathways." (PMID 38781365, 2024). "STK33 has been found to have mutations in patients with asthenozoospermia in Pakistan." (PMID 37146716, 2023). "Therefore, it is reasonable to observe mutations of STK33 in NOA patients, and its mutations led to asthenozoospermia or oligoasthenoteratozoospermia in mice." (PMID 37146716, 2023).
hypopharyngeal squamous cell carcinoma (2 papers, 2015 to 2019). "This study was aimed to investigate whether STK33 had the effect on hypopharyngeal squamous cell carcinoma (HSCC) and relevant genes, as well as the potential relation to ERK1/2 pathway." (PMID 25603720, 2015).
Obesity (2 papers, 2013 to 2015). Accumulation of substantial excess body fat. "Furthermore, two other loci, one close to the NEGR1 gene and another near STK33 were also associated to obesity in some studies and the NEGR1 gene has been independently associated with obesity in a pediatric cohort." (PMID 24267414, 2013).
pancreatic neuroendocrine tumor (2 papers, 2020 to 2022). Pancreatic endocrine tumor, also known as pancreatic neuroendocrine tumor (PNET), describes a group of endocrine tumors originating in the pancreas that are usually indolent and benign, but may have the potential to be malignant. "Enforced serine/threonine kinase 33 expression promotes the growth of pancreatic neuroendocrine tumor via activating PI3K/Akt/mTOR pathway." (PMID 32969473, 2020). "In addition, serine/threonine kinase 33 (STK33) is involved in pancreatic neuroendocrine tumor (PNET) growth and progression via PI3K/AKT/mTOR pathway activation." (PMID 36077529, 2022).
asthma (1 paper, 2025). "Single-cell RNA sequencing revealed upregulated STK33 expression in bronchial epithelial cells from patients with severe asthma." (PMID 41121245, 2025). "Collectively, these findings indicate that thrombin induces IL-8/CXCL8 release through the ERK/STK33/c-Myc pathway, highlighting STK33 as a potential therapeutic target in severe asthma." (PMID 41121245, 2025). "In this study, we investigated whether STK33 mediates thrombin-induced IL-8/CXCL8 release from airway epithelial cells in severe asthma." (PMID 41121245, 2025). "Immunofluorescence staining indicated increased coexpression of STK33 and macrophage inflammatory protein 2 (murine homolog of IL-8/CXCL8) in the airway epithelial cells of mice with ovalbumin- and house dust mite–induced asthma." (PMID 41121245, 2025).
autoimmune disease (1 paper, 2022). A disorder resulting from loss of function or tissue destruction of an organ or multiple organs, arising from humoral or cellular immune responses of the individual to their own tissue constituents. "Some of these genes are already therapeutic targets in other autoimmune diseases, for example, the STK33 inhibitor for rheumatoid arthritis treatment." (PMID 35638288, 2022).
Azoospermia (1 paper, 2023). Absence of any measurable level of sperm,whereby spermatozoa cannot be observed even after centrifugation of the semen pellet. "Herein, we identified two loss-of-function mutations of STK33 in seven individuals with non-obstructive azoospermia." (PMID 37146716, 2023). "Serine/threonine kinase 33 showed two loss-of-function mutations in the patients of non-obstructive azoospermia, which could cause defects in sperm formation in mouse." (PMID 37146716, 2023).
colon cancer (1 paper, 2017). "MIA PaCa2 pancreatic and HCT-116 colon cancer cells were transduced with either scrambled oligonucleotide or STK33-specific shRNAs and seeded on the surface of CAM, eight days after egg fertilization." (PMID 29100402, 2017). "Surprisingly, overexpression of STK33 in hypoxic HCT-116 colon cancer significantly boosted HIF-1α promoter activity beyond the levels achieved by hypoxic cells transduced with empty vector (lane 5 vs. lane 3)." (PMID 29100402, 2017).
diffuse large B-cell lymphoma (1 paper, 2025). "In addition, the strong positive correlation between STK33 and CCAR1 expression was also observed in liver hepatocellular carcinoma and diffuse large B‐cell lymphoma." (PMID 40908551, 2025).
leukemia (1 paper, 2023). A malignant (clonal) hematologic disorder, involving hematopoietic stem cells and characterized by the presence of primitive or atypical myeloid or lymphoid cells in the bone marrow and the blood. "Next, THP-1 (KRAS-independent, STK33-independent), NOMO-1 (KRAS-dependent, STK33-dependent), and SKM-1 (KRAS-dependent, STK33-dependent) leukemia cell lines were used to compare the anticancer effect of Z29077885 to those of BRD-8899 and ML-281." (PMID 38087254, 2023).
lung fibrosis (1 paper, 2022). "Based on the evidence that epithelial cells differentiate into myofibroblasts through the EMT and that myofibroblasts promote lung fibrosis, DCLK1 and STK33 may serve as therapeutic candidates for IPF." (PMID 35130915, 2022).
male infertility (1 paper, 2023). The inability of the male to effect fertilization of an ovum after a specified period of unprotected intercourse. "To evaluate the association of the STK33 functional variations with human male infertility, we sequenced the 16 exons and the intron boundaries of STK33 gene in a cohort of 620 patients with NOA." (PMID 37146716, 2023). "STK33 is a fibrous sheath regulatory kinase essential for spermiogenesis and male infertility." (PMID 37146716, 2023).
myeloma (1 paper, 2022). "Moreover, the dual blockade of RSK2 and AKT exerted robust molecular effects on critical gene sets associated with myeloma pathophysiologies, such as those with MYC, mTOR, STK33, ribosomal biogenesis, or cell-extrinsic stimuli of soluble factors, in HMCLs." (PMID 35328342, 2022).
teratozoospermia (1 paper, 2024). "STK33 is specifically required in male germ cells for spermatid differentiation, and Stk33 knockout male mice are sterile secondary to teratozoospermia and sperm immotility." (PMID 38781365, 2024).
tyrosinemia (1 paper, 2023). An autosomal recessive inherited metabolic disorder caused by mutations in the FAH, HPD, and TAT genes. "For instance, vimentin is a substrate of STK33 and participates in photoperiod regulation in the endocrine system; ERK2 is another substrate of STK33 and regulates tyrosinemia and tyrosinemia-associated neurological disorders." (PMID 37146716, 2023).